C3 (complement C3)
Diseases named in the same sentence as C3 in open-access papers (continued):
Sharing a sentence is not in itself a finding about the gene and the disease.
anemia (48 papers, 2008 to 2026). A reduction in the number of red blood cells, the amount of hemoglobin, and/or the volume of packed red blood cells. "In this case, risk factors for malignant lymphoma included low levels of C3, anemia, and multiple small lymphadenopathies detected by abdominal CT." (PMID 23151312, 2012). "The patient presented with profound anemia and laboratory evidence of hemolysis, with a positive direct antiglobulin test demonstrating both IgG and complement (C3) involvement, consistent with mixed AIHA." (PMID 42299187, 2026). "With this aim, the anti-C3 monoclonal antibody pegcetacoplan was developed and has demonstrated improvement in anemia in these patients." (PMID 40276419, 2025). "In this study purpura, parotid enlargement, anaemia, leucopaenia, lymphocytopaenia, hypergammaglobulinemia, low C3 and low C4 were all found to be significant predictors of NHL, but only hypocomplementaemia and lymphocytopaenia were independent risk factors." (PMID 38621708, 2025). "Terminal inhibitors such as eculizumab effectively block C5 cleavage and intravascular hemolysis, yet many patients still develop anemia, reticulocytosis, and fatigue from C3-mediated extravascular hemolysis." (PMID 41383613, 2025). "The recently approved C3 inhibitor pegcetacoplan, designed to block extravascular hemolysis, has been shown to improve anemia and hemolytic laboratory markers to a greater extent than eculizumab in patients with PNH." (PMID 39596172, 2024). "Severe anemia was observed in patients with CFH variants (38%), while C3 levels varied depending on complement abnormalities: indeed, half of the patients with C3 and MCP variants and 89% of the patients with anti-CFH antibodies showed decreased levels of C3." (PMID 37833944, 2023). "Compared with non-nephropathic children with early CS, those with nephropathy had higher frequency of hepatosplenomegaly, fever, edema, gastrointestinal (GI) symptoms, and anemia, as well as decreased C3 levels." (PMID 37667269, 2023). "Proximal inhibitors (C3, factor B and D inhibitors) show dramatic efficacy on extravascular hemolysis and in improving residual anemia while on anti-C5 agents." (PMID 36698833, 2022). "Xerophthalmia and anti-SSA/Ro52 were found to be negatively associated with renal involvement while histological positivity of LSGB, reduced C3, hypoalbuminemia and anemia were all significantly more common in the renal disease group." (PMID 33042142, 2020). "It has been reported that complement plays a role in the occurrence of anemia in the course of malaria infection by opsonization of unparasitized RBCs with C3 fragments which in turn can lead to phagocytosis of RBCs." (PMID 31760954, 2019). "70% cases with hypocomplementemia and 90% patients with anemia resulted in a mean complement C3 of 0.8 ± 0.2 g/L and an average Hb of 90.5 ± 22.9 g/L, respectively." (PMID 29416818, 2018). "However, anemia persisted in many patients due to both intravascular and, especially, extravascular complement component 3 (C3)-mediated hemolysis." (PMID 40276419, 2025). "Younger patients more frequently had reduced C3 complement and anemia." (PMID 40650238, 2025). "Another key feature is the development of autoimmune hemolysis, as evidenced by worsening anemia despite parasite clearance and a complement C3-positive direct antiglobulin test, highlighting complement-mediated hemolysis as an emerging complication of babesiosis." (PMID 41220440, 2025). "Younger individuals had higher IgG/IgA, more anemia, and reduced C3." (PMID 40650238, 2025). "Additionally, both conditions can present with certain laboratory findings, including anemia, liver and kidney function abnormalities, and a decrease in the C3 fraction of the complement." (PMID 37374366, 2023).
anemia (continued). "Patients with lower serum C1q levels (<40.97 μg/ml) showed significantly higher levels of SLEDAI (P < 0.001), significantly lower levels of C3 (P < 0.001), and significantly higher incidence of anti-ds-DNA antibody (P = 0.003), hematuria (P = 0.021), and anemia (P = 0.004)." (PMID 23510032, 2013). "In patients treated with C5 inhibitors, anaemia may persist or recur as a consequence of residual IVH, or C3-mediated EVH." (PMID 39201278, 2024). "Non-amyloid patients had a higher frequency of anemia (P = 0.003), and a higher frequency of low serum C3 (P < 0.001) and C4 (P = 0.007), than those with amyloidosis." (PMID 36216844, 2022). "Considering anemia, the group of SLE-a patients showed a strong correlation of RDW with serum IL-6 (r = 0.894, p < 0.001) in addition to PLR with TNF (r = 0.743, p < 0.025) and an inverse correlation with C3 complement (r = 0.538, p < 0.05)." (PMID 35620179, 2022). "Since chronic inflammation usually leads to leukocytosis, anemia, thrombocytosis, and elevated ESR, CRP, C3, and C4, laboratory tests including WBC, Hb, PLT, ESR, CRP, C3, and C4 are routinely performed at our clinics to provide another objective parameters for JIA evaluation." (PMID 33926518, 2021). "Laboratory investigations showed non regenerative anemia, eosinophilia, elevated erythrocyte sedimentation rate, elevated transaminases and LDH; positive ANA, anti-double-stranded DNA, anti-nucleosome, antihistone, RF and CCP; low levels of C3 and functional CH50 complement." (PMID 36096831, 2022).
glomerular disease (42 papers, 2012 to 2026). "Complement component 3 (C3), as a protein-coding gene, participates in the genesis and development of numerous diseases, including C3 deficiency, autosomal recessive, and glomerulopathy." (PMID 40396123, 2025). "C3GN is a rare glomerular disease associated with dysregulation of the alternative pathway (AP) of the complement system, characterized by predominate C3 deposits with little immunoglobulins deposition in the kidney." (PMID 40342409, 2025). "Alterative pathway dysregulation has been found approximately in 50–70% of patients with C3-glomerulopathy (glomerular C3 deposition) and immune complex-associated membranoproliferative glomerulonephritis (glomerular Ig and complement deposition)." (PMID 38003705, 2023). "Various glomerular diseases are associated with the deposition of C3 in the glomeruli." (PMID 38921822, 2024). "Pegcetacoplan, a targeted C3 and C3b inhibitor, may mitigate complement-mediated kidney damage in C3G and other glomerular diseases in which complement may have a pathogenic role." (PMID 38025230, 2023). "This dysregulation of the complement system caused by a long-term C5 inhibition is typically observed in patients with glomerular disease, who develop C3-associated deposits in the kidney comparable to those developed by patients with deficiencies in CFH and CFI28,43." (PMID 34001980, 2021). "However, glomerular diseases caused by mechanisms other than alternative complement dysregulation may occasionally satisfy “C3-dominant deposition with scanty immunoglobulins” as stated in the current consensus report." (PMID 27878657, 2017). "Concordantly, an appropriate evaluation of the complement system should be undertaken if immunofluorescence microscopy reveals a complement-dominant pattern, suggesting the possibility of C3 or C4 glomerulopathy." (PMID 40507864, 2025). "In a biopsy series of 217 diabetic patients where DKD was the only glomerular disease diagnosed, 53.9% had C3 deposits primarily within mesangium." (PMID 37492933, 2023). "Based on the findings, the IF-F technique resulted in a higher number of positive immunofluorescent signals of C3 in all investigated glomerulopathies in comparison to the IF-P technique." (PMID 36226196, 2022). "Glomerular FHR5 was identified in similar mesangial distribution to IgA and C3 in all IgAN cases from a biopsy series of glomerular diseases from Australia." (PMID 34379175, 2021). "Dense deposit disease (DDD), a subtype of complement component 3 (C3) glomerulopathy (C3G), results from alternative complement pathway hyperactivity leading to membrane attack complex formation." (PMID 33329990, 2020). "Compared with previous studies, our study included more parameters, including C3, C4 and C1q, etc., all of which are known as important biomarkers for common glomerular diseases with NS." (PMID 32928127, 2020). "Although C3 is the main driver of the disease, C5aR blockage is suggested to add substantial benefit for C3 glomerulopathy patients, which is supported by positive findings with eculizumab in prospective clinical trials." (PMID 33362783, 2020). "The area under the ROC curve (AUROC) of the IgA/C3 ratio in distinguishing IgAN among primary glomerular disease was 0.767 in the full cohort, and 0.734 in the PSM cohort." (PMID 31039758, 2019). "C3 glomerulonephritis is a rare glomerulopathy characterized at renal biopsy by C3 deposition, alone or with scanty immunoglobulins, as well as by an electron-dense material in mesangium, subendothelial and subepithelial space." (PMID 29592796, 2018). "Because clinical courses and prognoses among glomerular diseases with dominant C3 deposition differ, further understanding the background mechanism, particularly complement dysregulation in C3G, is needed." (PMID 27878657, 2017).
glomerular disease (continued). "A complement related-glomerular disease was suspected, because of the membranoproliferative pattern with the intense C3 deposits observed in the biopsy and the persistently decreased C3 serum levels." (PMID 27146825, 2016). "Compared with other glomerular disease controls, C3G showed glomerular upregulation of complement C3 with possible interactions with ITGAX (CD11c), a likewise upregulated integrin subunit which in turn had potential interactions with other highly enriched ECM-related proteins." (PMID 40416397, 2025). "Additionally, we successfully demonstrated complement inhibition and a reduction in renal complement deposition in an in vivo C3 glomerulopathy mouse model through the administration of recombinant TSP-1." (PMID 40338657, 2025). "The spectrum of glomerular diseases is abnormal control of complement cascade activation, whose actions are considered a part of the innate immune system, procuring an immune complex deposition of fragments of C3 in glomeruli." (PMID 40365108, 2025). "Interestingly, the inheritance of the miRSNP 1936T allele was significantly associated to chronic renal failure in a cohort of 78 patients diagnosed with complement factor H-related protein 5 (CFHR5) nephropathy (also known as C3-glomerulopathy)." (PMID 24204837, 2013). "Recent advances in complement-targeted therapies—including inhibitors of C3, C5, factor B, and MASP-2—are entering glomerular disease trials, with early evidence of efficacy in proteinuria reduction and slowing of glomerular injury." (PMID 41792651, 2026). "The AUROC for the IgA/C3 ratio was 0.767 in the full cohort, and 0.734 in the PSM cohort in distinguishing IgAN among primary glomerular disease." (PMID 31039758, 2019). "The C3F allele was associated with rapid progression of eGFR loss, defined as loss of at least 3 ml/min/1.73 m2 per year; glomerular C3 deposition; and progression of CKD in patients with IgAN, but not those with other glomerulopathies." (PMID 34379175, 2021). "The higher serum IgA/C3 ratio in IgAN patients compared to that in non-IgAN glomerular disease patients was driven by not only a significantly lower C3 level but also a significantly higher IgA level." (PMID 30941137, 2019). "Some of these glomerulopathies have not been reported in the literature to be associated with CPI use (MPO-ANCA positive pauci-immune glomerulonephritis, C3 staining, or AA amyloid)." (PMID 30612580, 2019). "In a Japanese study including 418 healthy individuals, and 195 IgAN and 111 non-IgAN glomerular disease patients, the pre-biopsy ratio of serum IgA to C3 (IgA/C3) was highest among IgAN patients." (PMID 30941137, 2019). "In the present study, the Masp1/3−/− MRL/lpr mice, lacking the LP and AP, had significantly reduced glomerular C3 deposition, pathological glomerular disease and albuminuria compared to their wild-type littermates." (PMID 29892304, 2018). "Renal disorders are categorised based on the presence of glomerular C3 deposits in the absence of significant immunoglobulin deposition and independent of glomerular disease patterns." (PMID 25380644, 2014). "However, our patient had no proteinuria, no urinary casts, and no biopsy evidence suggesting glomerular disease, and her C3 level was the only abnormal immunological finding." (PMID 40995257, 2025).
leukopenia (41 papers, 2012 to 2025). "The results indicated that ascites, hydronephrosis, leukopenia, decreased C3 level, and increased IgA level were independently associated with LEn." (PMID 34565417, 2021). "The diagnosis of SLE was made according to the European League Against Rheumatism and the American College of Rheumatology 2019 (EULAR/ACR2019) diagnostic criteria with a score of 19 (fever, leukopenia, alopecia, rash, pleural or pericardial effusion, and low C3 and C4)." (PMID 36414954, 2022). "For example, all patients showed leukopenia, decreased complement C3 and C4 levels, and an increased ESR before treatment." (PMID 37352070, 2023). "The diagnosis of SLE was made according to EULAR/ACR2019 diagnostic criteria with a score of 19 (fever, discoid lesion, leukopenia, thrombocytopenia, Coombs’ test positive, low C3, and anti-Sm antibody positive)." (PMID 36414954, 2022). "The patient showed leukopenia, lymphopenia, serum creatinine elevation with proteinuria and hematuria, decreased serum C3 level, and was positive for anti-double stranded DNA antibody, anti-nuclear antibody, and direct Coombs test." (PMID 35363197, 2022). "Multivariate analysis provided significant correlations between low C3, C4 levels and leukopenia (P < .001 and .0001, respectively), and between low C3, C4 and treatment retention time (P = .020, P = .049)." (PMID 35713462, 2022). "Leukopenia (white blood cell count < 4.2 × 109/L) occurred in 18 (16.7%) patients; C3 and C4 were low in 11 and 14 of these patients, respectively." (PMID 35713462, 2022). "Statistically significant correlation was found between the occurrence of leukopenia and the development of low complement C3 and C4 levels (P < .0001 and P < .001)." (PMID 35713462, 2022). "Laboratory examination indicated positive for antinuclear antibody (ANA) (1:160), leukopenia, increased urinary protein, decreased C3/C4, and normal BP180." (PMID 34805210, 2021). "Lastly, leukopenia, hypoalbuminemia, and lower levels of C3 and C4 are found in patients with DVM." (PMID 41427449, 2025). "Furthermore, low levels of C3 and leukocytes (leukopenia) also preceded an episode with decreased degradation with OR 3.0 (1.3 to 7.0) and 5.8 (1.6 to 21.5), respectively." (PMID 23945056, 2013). "Certain parameters such as renal involvement, splenomegaly, low C3 level, low C4 level, lymphopenia, leukopenia, and anti-Sm & anti-Jo-1 antibody were found to be significantly different among the age groups, while SLEDAI score at onset of SLE was higher with increased age of onset." (PMID 22551316, 2012). "As laboratory markers, low C3 and anti-dsDNA antibody positivity indicate higher SLE activity, and leukopenia and lymphopenia indicate hematologic involvement of SLE, suggesting that serum IGHG3 levels are correlated with lupus activity." (PMID 37108090, 2023). "The following factors were closely associated with fever: patient age, treatment history, SLEDAI score, enlarged liver, spleen and lymph nodes, low hemoglobin, leukopenia, CRP, complement C3, albumin, anti-dsDNA antibody, glucocorticoids, and cyclophosphamide." (PMID 30847312, 2019). "Pubescents showed significantly more renal involvement, leukopenia and lupus anticoagulant (LAC) positivity, along with lower C3 and C4 levels, when compared with prepubescents." (PMID 22551316, 2012). "Persistent leukopenia was observed in 8% and 5.3% of patients with normal C3 and C4 levels, respectively, as opposed to 47% and 42% of patients with low C3 or low C4, respectively." (PMID 35713462, 2022).
glomerulosclerosis (39 papers, 2012 to 2024). A hardening of the kidney glomerulus caused by scarring of the blood vessels. "A transcriptome and immunohistochemical analysis of human kidney biopsies (stages III-IV of DKD) revealed that about 50% of all DKD cases have an increased glomerular deposition of C3 compared to healthy controls, associated with increased glomerulosclerosis." (PMID 38338666, 2024). "Low C3 (<0.8 g/l, found in 26 (28%) patients) was associated with a higher proportion of glomerular sclerosis and a poorer kidney involvement, relative to the normal C3 group." (PMID 37475859, 2023). "These macrophages also were negatively correlated with serum albumin level (r = −0.331, P = 0.014), while positively associated with complement 3 (C3) deposition (r = 0.300, P = 0.026) and the severity of glomerulosclerosis (r = 0.276, P = 0.041)." (PMID 34095170, 2021). "Correlation analysis showed that the total macrophage count was negatively associated with serum albumin level, while positively associated with C3 deposition and the severity of glomerular sclerosis." (PMID 34095170, 2021). "According to this theory, C3 deposits in the mesangium causes severe histological lesions such as glomerulosclerosis or crescent formation." (PMID 34711174, 2021). "Accordingly, C3 may play a role, either through C3aR activation or C3dg deposition, in inducing glomerular capillary wall injury, leading to proteinuria, podocyte loss, and glomerulosclerosis in C3G." (PMID 32447506, 2020). "This study showed that both decreased circulating C3 levels and mesangial C3 deposition were associated with deterioration of kidney function in patients with IgAN independent of heavy proteinuria and other unfavorable histopathologic features such as glomerular sclerosis or interstitial fibrosis." (PMID 22792353, 2012). "Patients with IgM and C3 co-deposition had a higher mean number of glomeruli involved in both segmental and global glomerular sclerosis." (PMID 37182061, 2023). "We observed that patients with low C3 levels had more severe glomerular sclerosis and poorer kidney survival than normal C3 levels." (PMID 35874697, 2022). "We found that percentage of glomerular sclerosis was higher in the low C3 group than the normal C3 group (p = 0.012), while there were no statistical differences in demographics, clinical, laboratory, and other pathological variables." (PMID 35874697, 2022). "The results of single-nephron proteomic analysis and immunohistochemistry suggested that complement factors C3, C8, and C9 are overactivated in solidified glomerulosclerosis." (PMID 33633132, 2021). "In terms of pathological features, macrophages count was positively correlated with C3 (r = 0.300, P = 0.026) and glomerular sclerosis (r = 0.276, P = 0.041)." (PMID 34095170, 2021). "Our previous study using single-nephron proteomic analysis and immunohistochemical staining suggested complement factors such as C3, C8, and C9 are overactivated in solidified glomerulosclerosis in patients with DN." (PMID 34043214, 2021). "Proteins of the complement system (complement C3/C9/C8γ) and those involved in lipid metabolism (apolipoprotein [Apo]E) were highly enriched in solidified glomerulosclerosis." (PMID 33633132, 2021). "In three small studies on reflux nephropathy, deposits of C5b-9 were not or scarcely found in histologically normal glomeruli—similarly to healthy kidneys—but as intense coarse granules in areas of glomerulosclerosis together with C3 and properdin." (PMID 33643288, 2020). "Although it is evident from these studies that the alternative complement pathway plays a role in the development of podocyte injury, proteinuria, and glomerulosclerosis, it is uncertain how C3 induces kidney injury." (PMID 32447506, 2020). "Mild and focal mesangial staining of polyclonal IgM and C3 in glomerulosclerosis area was identified in 23 (19.8%) and 32 (27.6%) cases." (PMID 30832362, 2019).